KLF3 (KLF transcription factor 3)
Diseases named in the same sentence as KLF3 in open-access papers (continued):
Sharing a sentence is not in itself a finding about the gene and the disease.
pancreatic cancer (13 papers, 2020 to 2025). "miR-21-5p modulates apoptosis in pancreatic cancer stem cells (PCSCs) by targeting Kruppel-like factor 3 (KLF3), a transcription factor implicated in an oncostatic function across various malignancies, including the regulation of apoptosis." (PMID 40710326, 2025). "The secreted exosomal miR-21a-5p from the M2 macrophage induced the differentiation and proliferation of pancreatic cancer stem cells by targeting KLF3 for attenuating the stemness of pancreatic cancer." (PMID 40548119, 2025). "To further explore the relationship between KLFs and the prognosis of patients with pancreatic cancer, univariate Cox regression was performed, and we identified 4 significantly prognostic genes (KLF3, KLF4, KLF5, KLF6) with p < 0.05." (PMID 38773440, 2024). "(2020) assessed the impact of miR-324–5p upregulation on the growth of pancreatic cancer cells by targeting Krüppel-like factor 3 (KLF3), a transcriptional repressor." (PMID 39007129, 2024). "In pancreatic cancer, M2 macrophage-derived exosomal miR-21-5p stimulated differentiation and activity of pancreatic cancer stem cells via targeting Kruppel-like factor 3 (KLF3)." (PMID 37047075, 2023). "Further experiments verified that silencing KLF3 expression inhibited pancreatic cancer progression." (PMID 37600783, 2023). "In another study, M2 macrophage-derived exosomal miR-21-5p was shown to negatively regulate KLF3 in pancreatic cancer stem cells and, thus, stimulate pancreatic cancer growth and proliferation." (PMID 37239940, 2023). "We also focused on analyzing the relationship between KLF3 abnormal expression and pancreatic cancer progression using in vitro and in vivo experiments, and identified KLF3 as an independent prognostic risk factor for pancreatic cancer." (PMID 37600783, 2023). "The data confirmed that KLF3 was one of the targets of miR-21-5p, and participated in the regulation of miR-21-5p on the cell differentiation and activities of pancreatic cancer stem cells." (PMID 35549815, 2022). "Overexpression of KLF3 suppressed cell proliferation and increased apoptosis in vitro, and it has also been demonstrated to be downregulated in human pancreatic cancer." (PMID 35345512, 2022). "MiR-21a-5p is upregulated in M2 macrophage-derived EVs and mediates the activities of pancreatic cancer stem cells via targeting krüppel-like Factor 3 (KLF3)." (PMID 35501802, 2022). "To confirm this view, we analyzed pancreatic cancer cell proliferation and apoptosis in cells with overexpressed KLF3." (PMID 32913892, 2020). "Our present study opens a new window to understand the role of miR-324-5p and its post-transcriptional regulation to KLF3 in the development and growth of pancreatic cancer via disorganizing proliferation and apoptosis." (PMID 32913892, 2020). "In this study, Zhang and colleagues report that miR-324-5p plays an important role in pancreatic cancer cell proliferation and apoptosis through downregulating the expression of KLF3." (PMID 32913892, 2020). "We revealed that miR-324-5p regulates the expression of KLF3, and thereby the cell proliferation and apoptosis of pancreatic cancer cells." (PMID 32913892, 2020). "In the current study, we report that the levels of miR-324-5p are inversely correlated with the expression of KLF3 in the progression of pancreatic cancer." (PMID 32913892, 2020). "In this study, we report that miR-324-5p regulates the proliferation and apoptosis of pancreatic cancer cells through regulating the expression of Krüppel-like factor 3 (KLF3)." (PMID 32913892, 2020). "We demonstrated that miR-324-5p contributes to cell proliferation and apoptosis in pancreatic cancer by targeting KLF3." (PMID 32913892, 2020). "As shown by quantitative reverse transcription PCR analysis and western blot analysis, the mRNA and protein levels of KLF3 were reduced in both human pancreatic cancer and in vitro cultured pancreatic cancer cells." (PMID 32913892, 2020).
pancreatic cancer (continued). "Our results suggest that miR-324-5p plays an important role in pancreatic cancer cell proliferation and apoptosis via downregulating the expression of KLF3." (PMID 32913892, 2020). "The data presented herein suggest that transcriptional downregulation of KLF3 via miR-324-5p participates in proliferation and apoptosis of pancreatic cancer." (PMID 32913892, 2020). "In addition, miR-21-5p from M2 macrophage-derived exosomes reduced the levels of KLF3 in the pancreatic stem cells derived from pancreatic cancer cell lines." (PMID 37239940, 2023). "KLF3 was abnormally expressed in a variety of tumors, which could effectively predict the prognosis of patients, and it was most obvious in pancreatic cancer." (PMID 37600783, 2023). "Inhibition of miR-324-5p or overexpression of KLF3 in pancreatic cancer cells led to reduced proliferation and increased apoptosis, as shown by decreased levels of proliferating cell nuclear antigen (PCNA) and increased levels of BCL2-associated X (BAX), respectively." (PMID 37239940, 2023). "Interestingly, a recent study revealed that KLF3 was a target of miR-21-5p and participated in the regulation of miR-21-5p on the differentiation and activity of pancreatic cancer stem cells." (PMID 35549815, 2022). "Because intervention of miR-324-5p and KLF3 inversely influences pancreatic cancer cell proliferation and apoptosis, we further asked whether miR-324-5p can regulate the expression of KLF3." (PMID 32913892, 2020). "Furthermore, we identified KLF3, a factor regulating pancreatic cancer cell proliferation and apoptosis, as a new direct downstream target of miR-324-5p." (PMID 32913892, 2020). "Because miR-324-5p is involved in the invasion and metastasis of human cancers, whether the miR-324-5p-KLF3 regulatory process could also impact on the progression of cancers other than pancreatic cancer needs to be further tested." (PMID 32913892, 2020). "Therefore, the expression of miR-324-5p is inversely correlated with that of KLF3 in human pancreatic cancer tissues and cells." (PMID 32913892, 2020). "Finally, we analyzed the role of KLF3 in pancreatic cancer by in vivo and in vitro experiments." (PMID 37600783, 2023). "Therefore, KLF3 may be an important regulator for pancreatic cancer cell proliferation and apoptosis." (PMID 32913892, 2020). "The basal expression levels of KLF3 were significantly higher in pancreatic cancer cell lines PANC-1 and BxPC-3 cells, which will serve as a tool cell for silencing KLF3 expression." (PMID 37600783, 2023). "Similarly to KLF2 and KLF3, KLF6 is another tumor suppressor whose levels are inhibited in PDAC tissues and whose overexpression reduces pancreatic cancer proliferation, migration, and invasion." (PMID 37239940, 2023). "The findings that the expression of KLF3 was reduced in both human pancreatic cancer and in vitro cultured pancreatic cancer cells suggest that KFL3 may be involved in the processes of pancreatic cancer cell proliferation and apoptosis." (PMID 32913892, 2020).
Obesity (6 papers, 2013 to 2023). Accumulation of substantial excess body fat. "KLF3 deficient mice are resistant to diet-induced obesity and glucose intolerance with an accompanying increase in adipolin expression." (PMID 33275602, 2020). "Given that transplantation with KLF3-deficient haematopoietic cells promoted resistance to obesity, we sought to identify the important cell types in this process." (PMID 32523103, 2020). "Several mechanisms are known for miR-144-3p to promote adipogenesis: from suppressing the FOXO1 and reducing its regulation of adiponectin to stimulating differentiation of adipocytes by direct targeting Klf3 and CtBP2, protective factors against obesity." (PMID 38139235, 2023). "Chimeric mice and a control cohort of untransplanted WT and Klf3−/− animals were fed a high-fat, high-sugar Western diet for 11 weeks in order to investigate resistance to diet-induced obesity and adiposity." (PMID 32523103, 2020). "On the other hand, levels of Il10 were reduced in the absence of KLF3, in line with recent findings that IL-10 blockade protects against diet-induced obesity and elicits browning of AT51." (PMID 32523103, 2020). "However, we cannot exclude the possibility that obesity-induced perturbations in the balance between KLF15 and KLF3 expression may affect adipolin expression." (PMID 24358263, 2013). "Our observations demonstrate that adipose KLF15 but not KLF3 was down-regulated by obesity or the inflammatory stimulus, suggesting that KLF3 has a minor role in regulation of adipolin expression in fat tissue under conditions of obesity." (PMID 24358263, 2013).
breast carcinoma (5 papers, 2020 to 2024). "So, in the current study, the association between the expressions of TPD52, KLF3, miR-124, and PKCε and clinicopathological attributes of breast cancer patients is also inferred." (PMID 33490232, 2020). "On the other hand, the decreased levels of KLF3 in breast cancer, acute myeloid leukemia, and osteosarcoma, and is thus linked to an inferior prognosis in breast cancer, acute myeloid leukemia and osteosarcoma." (PMID 38305787, 2024). "Expression level of TPD52 was found to be elevated while KLF3, miR-124, and PKCε genes were downregulated in breast cancer patients in comparison to controls." (PMID 33490232, 2020). "So, the goal of the current study is to analyze the expression pattern of TPD52, KLF3, miR-124, and PKCε in breast cancer patients as well as to predict their possible correlation with clinicopathological characteristics of breast cancer." (PMID 33490232, 2020). "The results indicated high expression of TPD52 (p = 0.0017) and low expression of KLF3 (p = 0.0048), miR-124 (p = 0.0048), and PKCε (p = 0.0043) in blood of breast cancer patients as compared to healthy controls." (PMID 33490232, 2020). "The fold change observed in samples has spotted the upregulation of TPD52 and downregulation of KLF3, miR-124, and PKCε in breast cancer." (PMID 33490232, 2020). "Reduced expression of KLF3 in breast cancer upregulates the KLF8 gene, which is actually downstream of FAK." (PMID 33490232, 2020). "The expression of TPD52, KLF3, miR-124, and PKCε in breast cancer patients was measured." (PMID 33490232, 2020). "However, validation of KLF3 expression on larger cohort size and unraveling of its molecular role in breast cancer will further strengthen its significance as a biological marker." (PMID 33490232, 2020). "Present study expression analysis also suggests the tumor-suppressor role of KLF3 in breast cancer." (PMID 33490232, 2020). "Considering the homology ratio of KLF3 with KLF4 and KLF4 tumor-suppressor role, it can be assumed that KLF3 might also function to inhibit carcinogenicity in breast cancer." (PMID 33490232, 2020). "Likewise, enhanced TPD52 expression and lower KLF3 expression in the metastatic group of patients in comparison to the control and nonmetastatic group can be considerably utilized for diagnosis purpose of breast cancer at the molecular level." (PMID 33490232, 2020). "Hence, the present study intends to find the expression pattern of KLF3, miR-124, TPD52, and PKCε in breast cancer patients which may serve as effective diagnostic biomarkers." (PMID 33490232, 2020). "The RNA samples isolated from the blood of breast cancer patients were analyzed by qPCR for the expression of TPD52, KLF3, miR-124, and PKCε." (PMID 33490232, 2020). "The focus of this study was to explore the influence of Krüppel-like factor 3 (KLF3), tumor protein D52 (TPD52), microRNA 124 (miR-124), and protein kinase C epsilon (PKCε) expression on breast cancer." (PMID 33490232, 2020). "Contrary to KLF3, in vitro results of the present study have shown the upregulated expression of TPD52 (2-fold) in breast cancer patients as compared to healthy controls." (PMID 33490232, 2020). "The expression of KLF3 was downregulated in stage I-IV, metastatic vs. nonmetastatic groups, in every molecular subtype (luminal A, luminal B, and triple negative), and in patients that were either on treatment or naïve to any kind of breast cancer treatment as compared to healthy controls." (PMID 33490232, 2020).
melanoma (5 papers, 2019 to 2023). A malignant, usually aggressive tumor composed of atypical, neoplastic melanocytes. "The data indicated that circ_0084043 regulated cell proliferation, apoptosis, and glycolysis by promoting the KLF3 expression in melanoma cells." (PMID 33817265, 2020). "We also screened and identified the target miRNA (miR-31) of circ_0084043 and the target mRNA (KLF3) of miR-31, revealing a potential role of circ_0084043 in the progression of melanoma." (PMID 33817265, 2020). "A previous study elucidated that KLF3 was highly expressed in melanoma cells and that KLF3 knockdown inhibited cell viability, migration, and invasion." (PMID 33817265, 2020). "Moreover, circ-ADAM9 was found to enhance the proliferation and glycolysis of melanoma cells by upregulating KLF3 through sponging miR-31." (PMID 35096421, 2022). "Similarly, we also found that KLF3 was upregulated in melanoma cell lines and that KLF3 overexpression abolished the effect of miR-31 enrichment on the activities of melanoma cells, suggesting that KLF3 was indeed an oncogene in melanoma." (PMID 33817265, 2020). "We examined the expressions of KLF3 in melanoma cell lines and found that miR-23a-3p could directly target and decrease the expression of KLF3." (PMID 31462890, 2019). "Firstly, we measured the expression of KLF3 in melanoma cell lines." (PMID 31462890, 2019). "Through regulation in the expression of KLF3 by miR-23a-3p, NEAT1/miR-23a mediated melanoma proliferation, migration, and invasion." (PMID 31462890, 2019).
osteosarcoma (4 papers, 2022 to 2024). A usually aggressive malignant bone-forming mesenchymal neoplasm, predominantly affecting adolescents and young adults. "Such activity has been correlated with the destabilization of KLF3 mRNA, skewing cellular behavior towards osteosarcoma advancement and metastasis." (PMID 38140058, 2023).
colon cancer (3 papers, 2021 to 2023). "The infiltration levels of all TIICs, including B cells, CD4+T cells, CD8+ T cells, neutrophils, macrophages, and dendritic cells, were favourably linked with the expression of KLF3, KLF5, and KLF6 in colon cancer." (PMID 35345512, 2022).
leukemia (3 papers, 2014 to 2022). A malignant (clonal) hematologic disorder, involving hematopoietic stem cells and characterized by the presence of primitive or atypical myeloid or lymphoid cells in the bone marrow and the blood. "To investigate the significance of Class I HDACs (HDAC1, HDAC2, HDAC3, and HDAC8), HDAC11, and Klfs (Klf1, KLf3, Klf4, and Klf7) in the pathogenesis of human leukemia, we used real-time RT-PCR to evaluate the expression of HDACs and Klfs in bone marrow samples from human leukemia patients." (PMID 25341045, 2014). "The genes in the leukemia cell line term were AFDN (alias MLLT4, chromosome 1, WHWT), KLF3 (chromosome 3, LR), RPS6, (chromosome 5, LR), and FCER2, MCOLN1, and PRAM1 on chromosome 20 (GSD)." (PMID 36482174, 2022).
osteoporosis (3 papers, 2022 to 2025). A condition of reduced bone mass, with decreased cortical thickness and a decrease in the number and size of the trabeculae of cancellous bone (but normal chemical composition), resulting in increased fracture incidence. "Our study further revealed that KLF3 participated in osteoblast proliferation, as well as the regulation of miR-21-5p on osteoporosis progression." (PMID 35549815, 2022). "In summary, BMSCs-derived exosomal miR-21-5p improved osteoporosis through regulating KLF3, providing a potential therapeutic strategy for osteoporosis." (PMID 35549815, 2022). "BMSC-derived exosomal miR-21-5p improved osteoporosis through regulating klf3." (PMID 39857294, 2025). "Additionally, miR-21-5p regulates KLF3 (Kruppel-like factor 3) to promote osteoblast proliferation, contributing to the improvement of osteoporosis." (PMID 41254685, 2025). "Recently, it was found that inhibition of KLF3 might improve bone mass during osteogenesis, suggesting the possible involvement of KLF3 in osteoporosis." (PMID 35549815, 2022). "To further understand the potential mechanisms of miR-21-5p on osteoporosis, we predicted the downstream target genes of miR-21-5p and identified KLF3, a well-known negative regulator of osteoporosis, and knockdown of KLF3 was reported to increase bone formation." (PMID 35549815, 2022). "In summary, our study revealed that BMSCs-derived exosomes could enhance osteoblast proliferation, and then improve osteoporosis via miR-21-5p mediated inhibition of KLF3 (Graphical abstract)." (PMID 35549815, 2022). "However, the regulatory mechanism of miR-21-5p and KLF3 in osteoporosis remains unclear." (PMID 35549815, 2022).
sarcoma (3 papers, 2017 to 2022). A usually aggressive malignant neoplasm of the soft tissue or bone. "DNA methylation-mediated KLF3 silencing augments the pro-metastatic miR-182 in human sarcoma cells." (PMID 35311620, 2022). "Additionally, epigenetic silencing of KLF3 increases expression of pro-metastatic miR-182 in human sarcoma cells." (PMID 28423541, 2017).
asthma (2 papers, 2020 to 2024). "Interestingly, TCF21 and KLF3 loci have been previously identified as asthma risk-associated GWAS loci." (PMID 39107801, 2024). "Another Kruppel-like factor KLF3 (associated with bronchial, distal fibroblasts, CD8+ cells) has also been shown in tissue-resident memory lymphocytes in asthma." (PMID 32900903, 2020).
cervical cancer (2 papers, 2022 to 2023). A primary or metastatic malignant neoplasm involving the cervix. "For example, decreased KLF3 expression in colorectal and cervical cancers is associated with lymph node positivity and poorer outcomes." (PMID 35081118, 2022).
lung adenocarcinoma (2 papers, 2022). A carcinoma that arises from the lung and is characterized by the presence of malignant glandular epithelial cells. "However, one study reported lower levels of KLF3 mRNA and protein expression in lung adenocarcinomas compared with adjacent normal tissues and more frequent loss of KLF3 expression in late- versus early-stage disease." (PMID 35081118, 2022).
lymph node metastasis (2 papers, 2019 to 2022). "KLF3 expression was shown to be lower in lung tissues, and it was found to be inversely associated with TNM stage and lymph node metastasis." (PMID 35345512, 2022). "We found that the levels of KLF3 expression were negatively correlated with the tumor, node, metastasis (TNM) stage and lymph node metastasis." (PMID 31486564, 2019).
soft tissue sarcoma (2 papers, 2017 to 2022). A malignant neoplasm arising from muscle tissue, adipose tissue, blood vessels, fibrous tissue, or other supportive tissues excluding the bones. "Recently, the Kruppel like factor-3 (KLF3) has been shown to repress the expression of miR-182 in soft tissue sarcomas (STS) where miR-182 has a pro-metastatic role." (PMID 28412746, 2017). "Previous results indicated that KLF3 is decreased expression in human soft tissue sarcomas." (PMID 35311620, 2022). "KLF3 inhibits the pro-metastatic miR-182 expression and human soft tissue sarcoma metastasis." (PMID 35311620, 2022).
and Lobular Carcinoma (1 paper, 2022). "Only Finak Breast Statistics found that KLF3/6/11/16 was highly expressed in invasive breast carcinoma stroma, while KLF13 was higher in Invasive Ductal and Lobular Carcinoma." (PMID 35033064, 2022).